IL6 (interleukin 6)
Diseases named in the same sentence as IL6 in open-access papers (continued):
Sharing a sentence is not in itself a finding about the gene and the disease.
cancer (continued). "The sustained release of TGF-β1, ROS and IL-6 leads to transformation of peritoneal mesothelial cells into activated fibroblasts (myofibroblasts), and in the case of PM, cancer associated fibroblasts (CAFS)." (PMID 32532126, 2020). "Serum IL-6 levels have been reported to be associated with the prognosis of and tolerance to chemotherapy in several types of cancer, as well as with early recurrence." (PMID 32138303, 2020). "GSVA analysis showed that cancer hallmark gene sets related to the inflammatory response, IL6-JAK-STAT3 signaling, and allograft rejection were upregulated." (PMID 33170151, 2020). "High levels of IL-6 have been implicated in promoting epithelial–mesenchymal transition and stem cell-like properties in cancer cells." (PMID 32326381, 2020). "Several multicenter studies have demonstrated that the presence of various polymorphisms in genes coding for ILs, such as IL-1, IL-6, and/or IL-8, is strongly associated with increased risks of cancer development." (PMID 32156252, 2020). "Together with IL-6, both factors have been found to positively influence cancer-associated fibroblast proliferation." (PMID 32488850, 2020). "In Kaplan–Meier analyses, only IL6 (p = 0.036) showed a significant association with cancer-specific survival, whereas CRP (p = 0.075) and CNTF (p = 0.084) demonstrated borderline values." (PMID 33066437, 2020). "It has been demonstrated that IL-6 is a potential biomarker in colorectal cancer patients and in cancer cell lines also associated with likelihood of cancer recurrence and cachexia." (PMID 33371214, 2020). "IL-6 levels in particular have been shown to correlate with weight loss and reduced survival in cancer patients." (PMID 33291708, 2020). "Recent studies have shown that higher levels of cytokine IL-6 secreted by M2 macrophages were not only detected in HCC patient serum but also associated with cancer stage and progression." (PMID 32283687, 2020). "Another pro-inflammatory cytokine associated with tumor growth is interleukin-6, which in the case of melanoma drives cancer progression as an autocrine stimulator." (PMID 32471255, 2020). "Several studies have shown an association between high serum YKL-40 and IL-6 and shorter OS in different types of cancers and in patients with severe inflammatory diseases, which limits their specificity." (PMID 32756596, 2020). "In most cases, IL-6 was high-expressed in cancer and associated with the progression of cancer, resistance to antitumor chemotherapy, and poor prognosis." (PMID 32134471, 2020). "The consequences of increased IL-6 levels on the decrease in hematocrit is further supported by studies showing that the use of recombinant IL-6 in patients with cancer causes plasma volume retention." (PMID 33198320, 2020). "It is well known that some types of cancer are associated with the mutation of proteins of the IL-6 axis that can significantly influence IL-6 signalling." (PMID 33114676, 2020). "Several studies have explored the association between the IL-6 -174 G/C polymorphism and the risk of cancer." (PMID 32859764, 2020). "In the BCC dataset, we subsetted macrophages, both B cell types, and cancer-associated fibroblasts (CAFs), which have high IL6 signaling." (PMID 33065980, 2020). "Excessive expression of IL-6 is the most common finding when investigating the association of inflammation and cancer." (PMID 32963755, 2020). "Overall, cytokines are divided into proinflammatory groups such as TNF-α, IL-1β, IL-2, and IL-6, which play a role in initiating chronic inflammation and activating the NF-κB pathway and are strongly linked to cancer growth." (PMID 32156252, 2020).
cancer (continued). "IL-6, in turn, is up-regulated in several cancers and is implicated in the ability of cancer cells to create bone metastases." (PMID 32283655, 2020). "Reduced IL‐6 levels following obstruction of activin A activities associate with reduced ability of the cancer cells to accelerate autophagy in non‐cancerous cells in vitro and the ability to cause cachexia in mice." (PMID 31436048, 2020). "Both IL-6 and activin A, prominent mediators of cancer-associated muscle wasting, can drive autophagy in muscle cells." (PMID 33291708, 2020). "Both IL-6 and IL-23 have been shown to be involved in immunoediting in carcinoma microenvironments and associated with poor prognosis." (PMID 32684831, 2020). "Cancer-associated fibroblast-secreted cytokines such as IL-6 influence the phenotype of neoplastic cells, including proliferation, migration, and angiogenesis." (PMID 31998649, 2019). "Chronic IL-6 signaling plays a crucial role in cancer-associated inflammation in both mouse models and in human disease." (PMID 31557902, 2019). "Previous studies have demonstrated a relationship between IL-6 overexpression and increased cancer risk." (PMID 31249807, 2019). "Among others, tumor necrosis factor-alpha (TNF-α) and interleukin-6 (IL-6) and IL-8 were found to play a crucial role in cancer cachexia contributing to muscle loss and lipid wasting by increasing protein breakdown and adipocyte lipolysis." (PMID 31717736, 2019). "IL-6 is implicated in various cancers in suppressing apoptosis and accelerating uncontrolled cell growth via activating growth factor and related signaling pathways." (PMID 31167516, 2019). "Accumulating evidence implied the close association of IL-6 with the incidence of DVT in cancer patients." (PMID 32117207, 2019). "IL-6, a multifunctional cytokine, is known to be associated with many different biological activities of cancer cells, including the inhibition of apoptosis and epithelial–mesenchymal transition." (PMID 31117164, 2019). "In clinical practice, the first association of IL-6 with cardiovascular disease and cancer was found in 1990." (PMID 31795299, 2019). "To accomplish this, we tested the therapeutic potential of Tocilizumab, an IL-6 receptor (IL-6R) blocker that inhibits IL-6 signaling implicated in both burn and cancer-induced WAT browning." (PMID 31740668, 2019). "When stratified by race, log-transformed IL-6 was associated with almost a 4-fold increased risk among African-Americans (HR: 3.88, 95% CI: 1.17–12.88), and a 5-fold increased risk of cancer mortality among Whites (HR: 5.25, 95% CI: 1.24–22.31)." (PMID 31448052, 2019). "Previous studies also reported an association of several cytokines (e.g., IL-6) with cancer-associated VTE." (PMID 31847343, 2019). "IL-6 is a prime stimulus for STAT3 activation and elevated serum levels of IL-6 have been associated with poor prognosis in various cancers." (PMID 31731457, 2019). "Various systemic autoimmune diseases and certain types of cancers have been associated with dysregulation in IL-6 production." (PMID 31523783, 2019). "A previous study had found that IL-6 is a direct target gene for let-7 miRNA, which was downregulated in cancer-associated MSCs." (PMID 31915680, 2019). "VEGF, SDF-1, and CTGF, which are associated with angiogenesis and chemoattraction of cancer and endothelial cells, and IL-6, which is associated with the proinflammatory response, have already been proven to be a downstream gene of HIF-1." (PMID 30800209, 2019). "In conclusion, baseline measures of IL-6, a biomarker of chronic inflammation, and higher overall inflammatory biomarker index was associated with increased risk of cancer mortality in this racially diverse prospective cohort." (PMID 31448052, 2019). "Increased serum concentrations of IL-6 were found in at least 13 types of cancer, and associated with advanced disease and poor prognosis." (PMID 30232514, 2019).
cancer (continued). "Previous reports revealed a dominant role of IL-6 in the regulation and maintenance of different types of cancer-associated stem cells." (PMID 31315262, 2019). "In the current work, DOX-induced upregulation of P-gp and IL-6 will not only cause resistance to DOX but also many other anti-cancer drugs, a phenomenon termed multi-drug resistance (MDR) which is a major cause of chemotherapy failure." (PMID 31623629, 2019). "After adjusting for age, sex, education, income, cancer site, and race, there was over a 6-fold increased risk of cancer mortality associated with the highest tertile of IL-6 (HR: 6.66, 95% CI: 2.70–16.43)." (PMID 31448052, 2019). "Jorvig and Chakraborty reported that zerumbone caused cell cycle arrest of prostate cancer cells at the G0/G1 phase followed by apoptosis, and reduced expression of multiple cancer-associated genes, including cyclin D1, IL-6, COX2, ETV1, and JAK2." (PMID 31394732, 2019). "IL-6 is a critical pleiotropic cytokine associated with innate immunity and cancer; it is known to inhibit expression of CXCL1, and is a prominent target for clinical intervention." (PMID 31114758, 2019). "The fact that the substantial loss of p-STAT3 is seen under conditions affecting only IL-6/IL-6R signaling suggests that the contribution of IL-11/IL-11R to maintaining constitutive p-STAT3 levels in these cancer cells is relatively small." (PMID 31491838, 2019). "Anti-IL-6/Stat3 and associated molecular pathways have shown great potential in anti-inflammation and cancer immunotherapy." (PMID 30922248, 2019). "Patients with advanced cancer have elevated levels of IL-6 which correlate to weight loss, anemia and depression." (PMID 31842339, 2019). "IL-6 is a prototypical cytokine which plays a pro-tumourogenic function in inflammation-associated cancers." (PMID 31771617, 2019). "As another well-known immunosuppressive secreted factor in the TME, interleukin-6 (IL-6) is also highly expressed in some EC cases, especially in cancer-associated fibroblasts (CAFs) from EC patients, including both ESCC and EAC patients." (PMID 31771653, 2019). "IL-6 has also been shown to have diagnostic or prognostic relevance in several diseases, including cancer." (PMID 31554173, 2019). "Elevated levels of IL-6 have been associated with various cancers including lung, liver, pancreatic, and colorectal." (PMID 30894857, 2019). "In race-stratified analysis, each unit increase in IL-6 was associated with increased risk of cancer mortality among African-Americans (HR: 3.88, 95% CI: 1.17–12.88) and Whites (5.25, 95% CI: 1.24–22.31)." (PMID 31448052, 2019). "Only a small number of studies have examined a possible association between IL‐6 expression and IL‐6 secretion with acquired or inherent drug resistance in cancer." (PMID 30582770, 2019). "Several studies have shown that a major function of IL-6 is to regulate and maintain different types of cancer-associated stem cells." (PMID 31315262, 2019). "Pro-inflammatory cytokines IL-2, IL-12 and IFN-γ are associated with good prognosis in cancer, whilst an increase of immunosuppressive cytokines IL-6, IL-10 and TGF-β correlates to poor outcome." (PMID 30232514, 2019). "Recent data from our group and others demonstrate that platinum activates cancer-associated fibroblasts in ovarian xenografts, thereby stimulating IL6 secretion, which in turn, transcriptionally upregulates ALDH activity." (PMID 30965686, 2019). "The expression of CXCL1, CXCL3, CXCL2, CCL20, and IL6 are enriched in residual cancer and are associated with lesser response the chemotherapy when highly expressed at baseline." (PMID 30967156, 2019).
cancer (continued). "The proinflammatory factors of IL‐1 and IL‐6 from TAMs have been accepted to promote cancer cells invasion which is probably associated with the up‐regulation of their receptors." (PMID 31222971, 2019). "IL-6 is an inflammatory cytokine produced by cancer associated fibroblasts and other components of cancer microenvironment." (PMID 31101063, 2019). "Previous research demonstrated that the IL-6/JAK–STAT3 pathway is aberrantly hyperactivated in many carcinomas, and hyperactivation was generally associated with unfavorable clinical prognosis." (PMID 31703694, 2019). "Recent reports suggested that most of the pro-inflammatory cytokines, including IL-2, IL-6, IL-1β and IL-10, are over-expressed at cancer specific sites and particularly linked to invasion and progression of sever HCC conditions." (PMID 29651140, 2018). "Serum IL-6 expression was an independent indictor for survival and a high expression level was associated with cancer development and progression in GC32,59." (PMID 29915371, 2018). "SNPs affecting MMP-9 and IL-6 have been evaluated as predisposing factors for DVT in cancer patients." (PMID 29872658, 2018). "Articles mentioning IL-6 and cancer in a diagnostic, prognostic or therapeutic context were included either in group one as primary articles with results entering this review’s results or in group two as supporting articles providing background information." (PMID 30038723, 2018). "Several recent meta-analysis have focused on the association between IL-6 promoter polymorphisms and cancer risk." (PMID 29552316, 2018). "Interleukin 6 (IL-6) is one of the most studied cancer-associated cytokines, and elevated levels of IL-6 have been found in primary RCC cultures, RCC cell lines, as well as in the serum from RCC patients." (PMID 29717134, 2018). "therefore, a greater number of original case-control studies must be performed to further evaluate the association between the IL-6 promoter polymorphisms and different cancer types." (PMID 29552316, 2018). "IL-6 has already been associated with breast density in genome-wide association studies on cancer-free breast tissue, where genetic variations in nine tagging single-nucleotide polymorphisms in the IL-6 gene were significantly associated with HMD." (PMID 30092832, 2018). "Several pro-inflammatory cytokines and their associated pathways, which are known to promote cancer cell proliferation in many cases, were implicated in typical responders throughout this study, including IL6, CCL20, CXCL8, TNF signaling, and IL-17 signaling." (PMID 29983870, 2018). "High expression of IL-6 is associated with different cancer types, such as esophageal cancer, non-small cell lung cancer, endometrial cancer, breast cancer, prostate cancer, lung cancer, chronic lymphocytic leukemia and diffuse large B-cell lymphoma." (PMID 29552316, 2018). "In contrast to TNF-α, circulating levels of IL-6 have been shown to correlate with weight loss in cancer patients, and importantly, IL-6 levels correlated with reduced survival." (PMID 29338749, 2018). "The results indicate that the GG and CC genotypes, respectively for both SNPs, are associated with increased risk of DVT in cancer patients by inducing the release of IL-6 with subsequent increment of MMP-9." (PMID 29872658, 2018). "F. nucleatum also acts as persistent anchor of biofilms in the cancer tissue and subsequent E-cadherin loss activates Wnt signaling and IL-6 driven Stat3 activation." (PMID 30412600, 2018). "A reduction of CRP and IL-6 by PA is also beneficial since there is an increased vascular risk with high levels of these biomarkers and even some cancers." (PMID 29401699, 2018). "Our results showed statistically significant association between IL-6 promoter and cancer risk and prognosis." (PMID 29552316, 2018). "As a rule, high levels of IL-6 are associated with aggressive forms of cancers and IL-6 levels can act as independent markers of prognosis in certain cancers." (PMID 30671025, 2018).
cancer (continued). "In a recent cohort study conducted among 6545 middle-aged adults, IL-6 serum level was able to predict all-causes and cancer-related mortalities over a period of 17 years." (PMID 29951282, 2018). "IL6 has been demonstrated to be involved in the development, progression and metastasis in several cancers and IL6 overexpression is associated with poor prognosis in NSCLC." (PMID 29970138, 2018). "The IL-6 signaling is aberrantly hyper activated in many types of cancer and is generally associated with a poor clinical prognosis." (PMID 30175384, 2018). "IL-6 was required for development of colitis-associated cancer and treatment with anti-IL-6 receptor antibody suppressed polyp growth in APCMin/+ mice." (PMID 29707119, 2018). "Cytokines have also been implicated in patient survival, with increased IL-6 levels at diagnosis associated with poor outcome in numerous cancers including NB." (PMID 29967609, 2018). "The roles of IL-6 in the progression of MM are discussed in this review, including roles in bone homing, cancer-associated bone loss, disease progression and drug resistance." (PMID 30671025, 2018). "To quantitatively analyze the association of IL-6 and metformin with cancer metastasis, we measured the expression of MMP9 by real-time polymerase chain reaction (qPCR)." (PMID 30308035, 2018). "Levels of IL-6 and other cytokines prior to initial chemotherapy have been associated with outcome in numerous cancers including NB." (PMID 29967609, 2018). "Dysregulation of the IL-6 cytokine is one of the biomarkers associated with inflammatory diseases, including cancer." (PMID 29794990, 2018). "Correspondingly, previous report showed that IL-6 treatment enhanced CD44 (variant 6) expression in cancer cells via STAT3 activation." (PMID 30473835, 2018). "Many studies have investigated the association between IL-6 and GI cancers, as well as other cancer types, resulting in an acknowledgment of a certain effect of IL-6 in developing and sustaining the neoplastic cells." (PMID 30038723, 2018). "It was also associated with the proliferation of cancer cells and immunosuppression, through the production of IL-6, TGF-β, and other immunomodulatory cytokines." (PMID 29854832, 2018). "The identification of the IL6/JAK/STAT3 signaling cascade as cooperative partner in HH/GLI‐associated cancers provides a new rationale for evaluating combined HH‐IL6 targeting in BCC to improve the therapeutic efficacy of SMO inhibitor treatments." (PMID 29987839, 2018). "Together, these data verify that exosomal gp130 is indeed causative for the observed STAT3 signaling, IL-6 secretion, morphological changes, and enhanced survival of BMDMs in response to cancer-derived exosomes." (PMID 29867925, 2018). "Catabolic pro-inflammatory cytokines associated with cancer cachexia include interleukin-6 (IL-6), interleukin-1 beta (IL-1B), tumor necrosis factor alpha (TNF-α), and interferon gamma (IFN-γ)." (PMID 30591621, 2018). "Further, over-expression of IL-6 gene has been clearly linked to elevated cancer risk and HCC prognosis." (PMID 29651140, 2018). "Interleukin-6 (IL-6) is a multifunctional cytokine that has been implicated in the etiology of cancer." (PMID 30135142, 2018). "Inflammatory cytokines are one of the critical mediators in inflammation-associated cancer, especially interleukin-6 (IL-6)." (PMID 30513726, 2018). "Elevated expression of IL-6 and its major effector have been implicated in the different stages of cancer development, including initiation, promotion, malignant conversion, invasion, and metastasis." (PMID 29552316, 2018). "Many cancer types have been shown to be associated with high serum IL-6 including colorectal, breast, and prostate cancer, as well as MM." (PMID 30671025, 2018). "Several SNPs of IL-6 gene have been identified to be associated with cancer risk, but the most popular studied SNP is IL-6 -174G>C (rs1800795) polymorphism." (PMID 30135142, 2018).